EGFR (epidermal growth factor receptor)
Diseases named in the same sentence as EGFR in open-access papers (continued):
Sharing a sentence is not in itself a finding about the gene and the disease.
tumor (continued). "Some liquid biopsy assays have been reported to have a lower sensitivity for EGFR mutations compared to tissue biopsy that may be attributed to sampling from different tumor cell populations as well as differing sequencing technologies." (PMID 35209919, 2022). "The identification of the EGFR gene copy number by FISH techniques may provide a more accurate diagnosis of high-risk populations after the complete resection of a tumor." (PMID 35565304, 2022). "The resistance of KRAS‐mutant tumour cells to alterations in EGFR signalling might result in the null association between hPDI and KRAS‐mutant CRC." (PMID 35998061, 2022). "Via a proteomic analysis, 912 proteins were identified in MVs from pleural effusion samples of three NSCLC patients, including several tumor-associated proteins such as EGFR, KRAS, BSG/EMMPRIN/CD147, CEACAM6, CLDN1, CLDN3, and RAB family proteins (e.g., Rab1, Rab3, Rab5, Rab6, Rab11, and Rab13)." (PMID 35158999, 2022). "A higher radiological severity score of LM could predict higher tumor cell counts in CSF, which in turn were associated with a higher detection rate of EGFR mutation." (PMID 35740489, 2022). "EGFR is a tyrosine kinase receptor that Homo—or heterodimerizes with ligands to cause autophosphorylation, which in turn regulates downstream signaling pathways leading to tumor proliferation, invasion, metastasis and angiogenesis." (PMID 35620280, 2022). "The high detection rate of EGFR mutations in this study might be related to the poor PS induced by high tumor burden in the patients." (PMID 34643820, 2022). "Nonetheless, tumors harboring EGFR mutations frequently have a reduced percentage group of CD8+ tumor-infiltrating lymphocytes (TILs), which may result in immunological dysfunction and a poor prognosis." (PMID 35479081, 2022). "Furthermore, the effects of EGFR gene mutation status and tumor mutation load (TMB) on TDG gene expression in the TCGA-LUAD data set were observed." (PMID 35814273, 2022). "For EGFR PET tracers without treatment analogue, e.g., 18F-MPG, 11C-PD153035 and 18F-IRS, studies have shown that tumor tracer uptake could be quantified and that this was predictive for the presence of an EGFR mutation and for TKI therapy response." (PMID 36313723, 2022). "Moreover, epidermal growth factor receptor (EGFR) is associated with cancer because tyrosine kinase activity is required for tumor survival, growth, and metastasis." (PMID 36234645, 2022). "Interestingly, the inhibition of uPAR association with β1integrin, or EGFR alone, induces cell dormancy, thereby resulting in tumor suppression." (PMID 35158766, 2022). "Our analysis identified a CRLM-specific signature that clearly discriminated metastatic samples from normal liver tissue and revealed a high degree of tumor heterogeneity in the genes of the EGFR and the WNT pathways, which have previously been associated with poor survival in CRC." (PMID 35565214, 2022). "The phosphorylation activity in the kinase domain of EGFR may also be irregulated by several mechanisms, including EGFR mutation and overexpression, which is commonly found in tumor cells." (PMID 35164092, 2022). "EGFRvIII oncogenic variant tumor cells are sensitive to EGFR tyrosine kinase inhibitors (TKIs)." (PMID 36184613, 2022). "A case study of a woman with multifocal GBM demonstrated a complete response of one of the tumour sites to osimertinib treatment; however, the disease progressed at the other tumour site, likely due to the heterogeneous nature of the patient’s EGFR mutation status." (PMID 36497413, 2022). "Moreover, uncommon EGFR mutations can appear as part of a compound mutations (2 or more EGFR mutations within the same tumor)." (PMID 35274704, 2022). "Resistance to EGFR-TKIs therapy is associated with high tumor heterogeneity." (PMID 35463360, 2022). "The mechanisms of EGFR overactivation in tumor development is mainly associated with EGFR." (PMID 35778755, 2022).
tumor (continued). "Not only this, although the docetaxel treatment reduces EGFR activation by inhibiting its being phosphorylated in the presence of EGF, the abnormal activation, mutation, and overexpression of EGFR played a vital role in the establishment of docetaxel resistance in tumor cells as well as PCa cells." (PMID 36338727, 2022). "It is considered that the progress of tumor biology and tumor microenvironment (TME) differences in NSCLC with EGFR mutation may be a new method to enhance the curative effect of ICIs." (PMID 36189266, 2022). "Indeed, studies using 18F-FLT in EGFR mutation positive NSCLC have shown that a decrease of 18F-FLT uptake in tumor lesions is associated with response to EGFR TKI treatment." (PMID 36313723, 2022). "Notably, several studies have shown the impact of EGFR-TKI treatment on PD-L1 expression, TMB and the tumor immune microenvironment in EGFR-mutated NSCLC." (PMID 36159795, 2022). "In addition, more M1 TAMs infiltrated in the tumor and in tumor+stroma were found in the EGFR mutation group than in the EGFR wildtype group (p<0.05)." (PMID 35265073, 2022). "For testing EGFR mutations, using DNA extracted from tumor tissues is the gold standard." (PMID 35681723, 2022). "In certain cases (e.g., case 1), RBM10 loss may mediate the escape from tumor cell apoptosis during initial treatment and before the subsequent emergence of acquired resistance mutations such as EGFR T790M that drive tumor cell proliferation." (PMID 35579943, 2022). "For these two situations, EGFR T790M which occurred during the tumor progression and medical treatment may be the major cause." (PMID 35031014, 2022). "Combined staining of EpCAM and EGFR as tumor–associated markers might explain the high sensitivity of our ISX protocol." (PMID 35681790, 2022). "Currently, the gold standard for assessing EGFR mutations is to analyze the tumor tissues." (PMID 36232650, 2022). "However, tissue samples are difficult to obtain for EGFR mutation analysis, and tumor heterogeneity has an impact on accurate detection of EGFR mutations." (PMID 35422977, 2022). "Positron emission tomography (PET) studies using EGFR TKI-based tracers have shown that EGFR mutational status could be identified, and that tracer uptake could potentially be used as a biomarker for tumor response." (PMID 36313723, 2022). "TRAK1 and EGFR mutations were present in 9 and 6 tumours from 7 and 4 patients, respectively." (PMID 35231161, 2022). "The underlying hypothesis is that a sustained inhibition of EGFR signaling would continuously eliminate sensitive clones of RAS WT tumor." (PMID 35761123, 2022). "Focusing on EGFR/K-RAS/MAPK/SIAH pathway activation as a major tumor driver in TNBC to risk-stratify patients and detect chemo-resistance may represent a significant step forward." (PMID 36176751, 2022). "The plasma genotyping of EGFR-mutant NSCLC is also highly valuable during treatment as an indicator of tumor response or disease progression by evaluating variant allelic fractions of genomic alterations and detecting the emergence of resistance mechanisms earlier." (PMID 36139444, 2022). "To examine whether the EGFR mutant status influenced the tumor mutation number, we determined the mutation numbers across EGFR mutation subtypes in NSCLC tumors from our cohorts." (PMID 36505399, 2022). "On binding to its ligand, the EGFR is auto-phosphorylated by intrinsic tyrosine/kinase activity, causing activation of several signal transduction cascades resulting in more aggressive tumor phenotypes." (PMID 36080307, 2022). "Blood samples from 19 patients had the same EGFR mutation as those in the tumor samples (63.3%)." (PMID 36192767, 2022). "Gefitinib and rapamycin synergistically inhibit advanced human NSCLC cell line (H1975, harboring EGFR T790M secondary mutation) proliferation and tumor formation by upregulating cell autophagy activities, thereby inducing cell autophagy–EGFR positive feedback regulation." (PMID 35887373, 2022).
tumor (continued). "Next-generation sequencing (NGS) of tumor biopsies has greatly expanded our knowledge on somatic mutations in NSCLC such as the deep genetic heterogeneity in tumors beyond epidermal growth factor receptor (EGFR) changes." (PMID 35783357, 2022). "The cluster centers corresponding to each patient’s tumor samples, excluding NATs, could successfully predict the EGFR mutational status by regularized logistic regression." (PMID 35360705, 2022). "A similar model could also characterize the time-curves of EGFR mutation and tumor sizes obtained from NSCLC patients." (PMID 35273301, 2022). "In addition, other CT image features that have been found to be related with EGFR mutation include the maximum tumor diameter, spiculated margins, and the air bronchial sign." (PMID 35422977, 2022). "This is also regarded as heterogeneity within the tumor bulk of GBM caused by EGFR aberration." (PMID 35814475, 2022). "The controlled release of LCN2 into the tumor microenvironment could cause effects on EGFR shuttling and on activation of EGFR by phosphorylation, as reported in a recent study." (PMID 35216088, 2022). "Therefore, the knockdown of the tumor EGFR by the THL-mediated RNAi therapy caused a suppression of the vascular density of the tumor." (PMID 35745855, 2022). "Alternatively, in recent years, imaging studies using radiolabeled EGFR TKI have shown that PET could potentially be of value for identifying EGFR mutation positive patients and predicting tumor sensitivity to EGFR TKI." (PMID 36313723, 2022). "Moreover, CSF tumor cells ≥ 1+ were associated with a higher CSF EGFR mutation detection rate (90.0% vs. 61.5%, p = 0.042)." (PMID 35740489, 2022). "Earlier studies suggested that constitutive activation of the EGFR signaling pathway in tumor tissues may be initiated by EGFR gene amplification or triggered by EGFR mutations." (PMID 36291859, 2022). "Next, to further check whether the antitumor effect was associated with its anti-proliferation and inhibition of EGFR signaling, tumor extracted from each group were prepared and analyzed for the expression levels of Ki-67 and P-ERK (Tyr202/204)." (PMID 36467103, 2022). "Interestingly, abnormal circ_0007618 and circ_0029426 expression was significantly correlated with tumor stage, lymphatic metastasis, and EGFR mutation (p < 0.05)." (PMID 35212617, 2022). "The tumor-specific DNA markers including point mutations in EGFR or BRAF genes, rearrangements involving ALK or ROS1 genes and fusions of NTRK1/2/3 genes along with tumor mutation burden (TMB) and PDL-1 RNA expression serve as guides in proper therapy selection." (PMID 35837614, 2022). "Both types of therapy have demonstrated efficacy in subsets of patients with certain tumor types, with TKIs exhibiting efficacy in, for example, NSCLC with EGFR-activating mutations, and anti-EGFR antibodies in tumor types such as metastatic CRC (mCRC), and SCCHN." (PMID 36185288, 2022). "Liquid biopsy can reliably identify somatic tumor-associated EGFR mutations in plasma." (PMID 35482671, 2022). "No statistical differences in age, sex, smoking history, pathological stage, mutation status of the epidermal growth factor receptor (EGFR), and microinvasion were evident between the patients with high or low drebrin+ T cell infiltration into the tumor cell nests." (PMID 36430217, 2022). "However, since EGFR mutations exist in high‐risk patients long before malignancy formation, it is more clinically relevant to test the anti‐tumor effects of agents in mice after oncogene induction." (PMID 35861366, 2022). "Patients with loss of LKB1 with KRAS or EGFR mutations denote an aggressive tumor phenotype, that might be due to the loss of LKB1 as a metabolic sensor; these patients might benefit from biguanide treatment." (PMID 35890085, 2022). "B7-H3 effects may be derived from the underlying cross-linking between EGFR signaling and B7-H3-induced signaling which share the majority of downstream cascades in tumor cells." (PMID 35590371, 2022).
tumor (continued). "Common and rare EGFR mutations may develop during the course of the disease affecting both the biological behavior of the tumor and the response to treatment." (PMID 35884398, 2022). "The prognosis of NSCLC patients may be assessed through components of tumor immune microenvironment, and ICIs treatment may be considered for those with some uncommon EGFR mutation subtypes." (PMID 35265073, 2022). "For surgical resected EGFR‐mutated patients, monitoring the recurrence of tumor is performed currently according to clinicopathologic risk stratification, which could be improved in some way." (PMID 35023616, 2022). "Combination EGFR-TKI treatment may decrease tumor growth and prevent the development of resistant variants." (PMID 35304574, 2022). "However, further mutations in the EGFR gene and of downstream effectors eventually allow tumours to overcome the TKI therapeutic block and resume uncontrolled proliferation." (PMID 35158954, 2022). "However, tumor mutation in EGFR and its amplification status are strongly associated with EGFR TKI therapy’s positive response." (PMID 36518665, 2022). "RBM10 deficiency decreased EGFR inhibitor efficacy in patient-derived EGFR-mutant tumor models." (PMID 35579943, 2022). "This patient’s tumor showed only stable disease (SD) on erlotinib therapy (6 months), followed by early progression that coincided with the acquisition of the drug-resistant T790M mutation of EGFR." (PMID 35579943, 2022). "Therefore, the selection of EGFR-TKIs should depend not only on the patients’ tolerability but also on the risk stratification for tumor progression." (PMID 35205720, 2022). "The high specificity of ctDNA for detecting tumour EGFR mutations provides confidence that a positive ctDNA test could be used in selecting NSCLC patients for treatment with EGFR TKIs." (PMID 35055414, 2022). "Tumor re-biopsy can be omitted in patients with positive EGFR mutations by liquid biopsy during PD." (PMID 36192767, 2022). "Moreover, erlotinib resistance can develop due to EGFR mutations, as demonstrated in EGFR-mutant tumor samples." (PMID 35814435, 2022). "Therefore, the continuous assessment of tumor EGFR mutation status during the course of disease is necessary for the better management of NSCLC patients, particularly for the early identification of the resistance mechanisms." (PMID 36232650, 2022). "EGFR-targeted molecular imaging is an attractive tool for evaluating in-vivo EGFR mutation status because it can non-invasively acquire the molecular and genomic characteristics of the tumor and whole-body." (PMID 35120180, 2022). "Therefore, KRAS mutation in CRCs is associated with more reduced survival, increased tumor aggressiveness, and resistance to anti-epidermal growth factor receptor (EGFR) targeted-therapies." (PMID 35562390, 2022). "EGFR mutation analysis must be performed using all obtainable tumor tissues of MPLC." (PMID 35740676, 2022). "A novel TKI CLN-081 causes persistent tumor regression in EGFR exon 20ins-driven mouse models." (PMID 36508072, 2022). "However, EGFR mutations in other tumor types including GC are much rarer, and their clinical significance is unclear." (PMID 36209270, 2022). "We found the differences in the highly expressed cancer-associated genes and the positive rate of EGFR exon 19 deletions among the tumor before and after treatment and tumor stroma, even though they were collected from tumors of the same patient or close regions of the same specimen." (PMID 36505794, 2022). "The basal tumors also demonstrate a high degree of mutations in the erbB family, and the treatment with an EGFR inhibitor might give an advantage in this tumor subtype." (PMID 36294884, 2022).
tumor (continued). "Local SBRT to the primary tumor in the early phase, at approximately the first month in our study, seemed to have good local control, with the possibility of eliminating tumor heterogeneity and thereby delaying targeted resistance in advanced EGFR-mutation-positive NSCLC treated with EGFR-TKI." (PMID 36556319, 2022). "This newly developed agent targeting wtEGFR could provide molecular imaging of wtEGFR-positive tumor and fundamental information for quantitative analysis of certain EGFR mutations in future studies." (PMID 35120180, 2022). "Specifically, if C797S and T790M mutations are on different chromosomes (in trans), tumor will retain sensitivity to the combination treatment of first- and third-generation inhibitors; while they are on the same chromosome (in cis), EGFR-TKIs alone or in combination are ineffective." (PMID 36482474, 2022). "These factors are closely associated with the positive expression of EGFR, where EGFR expression could play a role in the mechanistic behind the tumor progression and metastasis, increasing the chance of death." (PMID 36188649, 2022). "Most SCLCs supposed to be switched from a NSCLC have occurred in EGFR-mutated tumours." (PMID 35456982, 2022). "Together, the representation of these features indicates tumor heterogeneous related to EGFR mutation phenotype, which provides an alternative non-invasive way easily to forecast EGFR status in routine CT diagnosis and supply a good supplement to biopsy in real clinical practice." (PMID 36052262, 2022). "In contrast, samples from patients that received systemic therapy prior to tumour sampling did show higher VAF of EGFR mutations, which were detected in four patients (10%) in our cohort, and a non‐statistically significant enrichment of chromosome 6 copy number deletions." (PMID 35231161, 2022). "In this study, 52 patients (51.5%) had different EGFR mutation statuses (16 patients had different mutations, and 36 patients had at least one EGFR-wildtype tumor), 20 patients had the same EGFR mutations (19.8%), and 29 patients (28.7%) had only EGFR-wildtype tumors." (PMID 35740676, 2022). "In addition, in one case, we detected the same EGFR exon 19 del mutation with cobas test as in the primary tumor sample, but the AmoyDx gave a wild-type result." (PMID 36277960, 2022). "In lung ADC, the first example of successful targeted therapy is the pharmacological inhibition of the epidermal growth factor receptor (EGFR) with increasing survival of patients with actionable tumor EGFR mutations receiving EGFR tyrosine kinase inhibitors (TKI)." (PMID 35267628, 2022). "Therefore, the selected DE-lncRNAs play crucial roles in EGFR-TKI resistance by regulating the target DE-mRNAs involved in tumor-associated pathways." (PMID 35571024, 2022). "The Tumor Microenvironment (TME) of patients with NSCLC harboring EGFR mutations displays peculiar characteristics and may modulate the antitumor immune response." (PMID 35742933, 2022). "At diagnosis, liquid biopsy could detect 19 cases (63.3%) among patients with EGFR mutations, as proven by tumor biopsy." (PMID 36192767, 2022). "This may be related to the palmitoylation site of EGFR, tumor types and the mutational environment within the tumor." (PMID 35637973, 2022). "A clinical study investigating the development of resistance in a patient initially sensitive to CTX analyzed both pre- and post-CTX tumor biopsies and found a missense mutation in the EGFR-ECD at the 465th position with a glycine to arginine substitution (G465R)." (PMID 35409179, 2022). "The main cause of skin toxicity is the targeting effect of anti-tumor drugs on wild-type EGFR." (PMID 35223483, 2022). "Moreover, studies that link the association of the severity of LM in brain images with CSF tumor cell counts and EGFR detection rates are limited." (PMID 35740489, 2022).